IL1B (interleukin 1 beta)
Diseases named in the same sentence as IL1B in open-access papers (continued):
Sharing a sentence is not in itself a finding about the gene and the disease.
cancer (continued). "Interestingly, CD8+ T cell infiltration upon injection of IL-1B overexpressing E0771 cancer cells mirrored the infiltration pattern of F4/80+ macrophages." (PMID 34290237, 2021). "Once activated, these NLRP3 inflammasomes may drastically promote cancer angiogenesis, endothelial cell proliferation, and immunosuppressive cell activation via releasing IL-1β and IL-18." (PMID 34588926, 2021). "This study reported for the first time that CK2 down-regulation in human cancer cells enhances the expression of SASP factors (IL-1β, IL-6, and MMP3) by NF-κB activation through two pathways: an SIRT1-dependent/AKT-independent pathway and an SIRT1/AKT-dependent pathway." (PMID 33401686, 2021). "Being cocultured with Panc-1 cells, M1 macrophages are enabled to polarize to M2 state due to the increased expression of M2 markers (Arg1) and decreased expression of M1 markers (IL-1β and iNOS), which could been shown the effect in cancer progression." (PMID 34722637, 2021). "Similar results were obtained by silencing IL-1β gene expression in cancer cells, which resulted in decreased infiltration by immunosuppressive cells (MDSCs, M2 macrophages) of orthotopic tumors, while the number of INFγ/GzmB producing CD8+ T cells was increased." (PMID 33840390, 2021). "In this regard, IL-1β blockade may generate adjunctive effects when combined with chemotherapies or other treatments in cancer." (PMID 34620838, 2021). "It has been demonstrated that inflammation in cancer is driven by IL-1β." (PMID 34602858, 2021). "Also, BTK inhibition impaired IL-1β processing and release in human primary macrophages from healthy donors, ibrutinib-treated cancer patients, and patients with Muckle–Wells syndrome—an autoinflammatory disease characterized by excessive production of IL-1β." (PMID 33818636, 2021). "Moreover, exosomes isolated from malignant ascites and amniotic fluid can induce pro-IL-1β expression and IL-1β secretion in THP-1 monocytic cells." (PMID 33754070, 2021). "In addition, the interaction between NF-κB and proinflammatory cytokines such as TNF-α and IL-1β is also involved in stimulating cancer cell proliferation, especially during chronic inflammation." (PMID 34079469, 2021). "Moreover, we decided to investigate, by immunohistochemistry staining, the expression of IL-1β, a pro-inflammatory cytokine related to cancer progression." (PMID 34681768, 2021). "The common denominator affecting inflammation and development of cancer is IL-1β level." (PMID 34094030, 2021). "Moreover, NLRP3 downstream, IL-1β, also stimulates the production of ROS that, in turn, induces DNA damage and cancer development in CRC." (PMID 33613533, 2020). "In addition, IL-1β also supports metastasis by promoting the transformation of cancer stem cells and the epithelial mesenchymal transition (EMT)." (PMID 33488930, 2020). "Although IL-1β and IL-1α share similar transducing pathways, they have different expression and activation processes, explaining why they have different biological and physiological effects in many diseases, notably cancer." (PMID 32635472, 2020). "Furthermore, even when IL-1β exposure was withdrawn, cancer cells sustained their acquired phenotype." (PMID 32635472, 2020). "The role of inflammatory IL-1β signaling in cancer is complex." (PMID 33322216, 2020). "Moreover, anti-cancer treatments are able to promote IL-1β production by cancer or immune cells, with opposite effects on cancer progression." (PMID 32635472, 2020). "Transcript levels of soluble factors often linked to cancer-promoting (CP) inflammation, such as IL-6, CXCL1, CXCL2, IL-1β, or G-CSF, were markedly higher in COX-competent compared to COX-deficient tumors, and their expression was unchanged in the absence of NK cells." (PMID 33220234, 2020). "Another mAb that inhibits IL-1β, gevokizumab, used in inflammatory disorders, could also be proposed in cancer treatment." (PMID 32635472, 2020).
cancer (continued). "A previous study indicated that IL-1β stimulates the activation of hypoxic signaling pathways in cancer cells that are critical for regulating and maintaining the characteristics of cancer stem cells (CSCs), including undifferentiated phenotype, self-renewal capacity, and immortality." (PMID 33613533, 2020). "Moreover, networks related to “cancer” and “development disorders” were among the top enriched “Disease” networks while IL-1β, the NF-ĸB complex and IKBKB were among the most highly enriched “Upstream Regulators”." (PMID 32456215, 2020). "Moreover, it raises the importance of Cathepsin B and the interest to develop inhibitor peptides targeting its interaction with NLRP3, an early and common event, to inhibit IL-1β production in inflammatory diseases or cancer." (PMID 32328491, 2020). "Celecoxib exhibits antitumoral effects in GBM cancer stem cells independently of IL-1β." (PMID 33205044, 2020). "Similar to IL-6, also IL-1β has been reported to play a complex role in inflammation and cancer." (PMID 33194755, 2020). "Similarly, the undifferentiated MPRO cells expressed higher levels of Il-1β, Ccl2, Ccl3, Ccl4, and iNos when cultured in the supernatant of cancer cells compared to SF media." (PMID 33049964, 2020). "Thus, an amplification loop between IL-1β and mutated-KRAS seems to increase cancer progression and drug resistance." (PMID 32635472, 2020). "Therefore, the fact that IL-1β is inducing the production of protumorigenic molecules is a central event during cancer progression." (PMID 33015196, 2020). "Hence, its role in predicting response to immune checkpoint blockade needs to be further evaluated, and further research is needed to assess the efficacy of IL-1β inhibitors with immunotherapy or other anti-cancer therapeutic agents." (PMID 32516941, 2020). "Together, these findings suggest that both GPER and IL-1β/IL1R axis contribute to hypoxia-decreased cancer cell spreading on the ECM protein fibronectin, according to previous data correlating the hypoxia-lowered cell-ECM adhesion to an increased invasion, intravasation and metastasis." (PMID 32778144, 2020). "The elevated expression of IL-1β has been observed in various human cancers." (PMID 32858855, 2020). "In addition to EMT, the chronic IL-1β exposure also increased and maintained expression of genes related to cell adhesion, cancer invasion, apoptosis resistance, and production of cytokines involved in immune responses." (PMID 31941995, 2020). "In addition, several common cancer-associated mutations, such as genetic alterations in KRAS and BRACA1, promote IL-1β expression." (PMID 33584721, 2020). "The importance of IL-1β can first be considered by its impact on cancer development or progression." (PMID 32635472, 2020). "The impact of IL-1β on angiogenesis has also been observed in different cancer models." (PMID 32635472, 2020). "Moreover, the inflammasome signalling can prime natural killer (NK) cells through IL‐1β or IL‐18 and exert anti‐cancer effects by specialized programmed cell death called pyroptosis and immune regulatory functions." (PMID 32725966, 2020). "IL-1β may stimulate expression of COX-2 and production of PGE2 synthesis in cancer-associated fibroblasts by activating COX-2 promoter activities." (PMID 32410839, 2020). "Accordingly, we proposed that the Akt/GSK-3β axis may be involved in the LDOC1-mediated suppression of IL-1β production and anti-cancer effects in OSCC." (PMID 33120999, 2020). "Collectively, the expression of NLRP3, caspase-1, GSDMD, and IL-1β protein was higher in cancer and atypical hyperplasia tissues than in benign endometrial tissues, significantly difference were observed in key pyroptotic protein caspase-1 and GSDMD (P < 0.05)." (PMID 31924176, 2020). "For all cancer patients, IL-1β had a high sensitivity of 71% and specificity of 59.5%." (PMID 32355279, 2020).
cancer (continued). "Furthermore, the roles of IL1β seem to be more direct in facilitating the transition from androgen-sensitive cancers to CRPC than the elimination processes of the immunoediting theory." (PMID 33322099, 2020). "The significant reduction of IL-1β secretion following pyrazinib (P3) treatment is a critical finding which may contribute to pyrazinib’s (P3) anti-cancer effect." (PMID 32694701, 2020). "The level of IL-1β produced, the type of producing cells, the microenvironment (immune cells or fibroblasts), the stage of the cancer, and the anti-cancer treatments used may all participate in the divergent effects of IL-1β." (PMID 32635472, 2020). "These and previous studies indicate that inflammasomes have diverse roles in cancer with some cancers benefiting from IL‐1β and IL‐18, whereas in others, the IL‐1 signaling pathway promoted cancer growth (Karki & Kanneganti, 2019; Karki, Man, & Kanneganti, 2017)." (PMID 32027447, 2020). "To conclude, we have highlighted in this review the pleiotropic effects of IL-1β in cancer." (PMID 32635472, 2020). "In addition, IL-1β is a vital neutrophil activator, and pro-survival cytokine and the elevated expression of IL-1β can also be the reason for the prolonged survival time of neutrophils in the cancer supernatant." (PMID 33049964, 2020). "However, this was mediated by the up-regulation of IL-1β in cancer cells which promotes neutrophil infiltration to the metastatic niche." (PMID 32706336, 2020). "Therefore, it is necessary to explore systematically the relationship between IL-1B-511/IL-1β mRNA and pathological changes of gastric mucosa from normal to carcinoma." (PMID 32382299, 2020). "It is also released by cancer cells under the inducer of IL‐1β from TAMs." (PMID 31222971, 2019). "The suppression of NLRP3 inflammasome in immune cells could be a novel strategy for anti-cancer therapy by reducing IL-1β secretion." (PMID 31439870, 2019). "Also, the neutrophils physically clustered with circulating 4T1 breast cancer cells support the cancer cell cycle progression, secreting IL-6 and IL-1β, and promote metastasis of cancer cells." (PMID 31474975, 2019). "Moreover, a subgroup analysis showed that the responsiveness of IL-1β was correlated with the overall survival rate of cancer patients." (PMID 31041568, 2019). "On the other hand, depending on its local doses, the role of IL-1β in cancer is still puzzling." (PMID 31480312, 2019). "As a matter of fact, IL-1β, arising from cancer-related inflammation, increases macrophage expression of cyclooxygenase (COX)-2, eventually leading to an increased production of prostaglandins, which bind prostanoid receptors on sensory terminals, resulting in CIBP." (PMID 30641973, 2019). "Although some types of cancer cells can release certain cytokines, cachectic cancer cells do not necessarily release catabolic cytokines such as TNFα, IL-6, and IL-1β, and the vast majority of circulating cytokines are generated by immune cells in response to cancer." (PMID 31480237, 2019). "A key feature of HPV-induced carcinogenesis, is that chronic inflammation is one of the main promoters of oncogenic pathway activation, and several studies have shown that the activation of IL-1β and IL-18 proteins by inflammasome increases the progression of different types of cancer." (PMID 31554368, 2019). "The abundant IL‐1β expression assists GC development by stimulating cancer cell proliferation." (PMID 31145543, 2019). "IL-1β is considered as an attractive target in cancer treatment." (PMID 31492049, 2019). "In esophageal cancer cells or cancer stem cells, metformin reversed the expression of several inflammatory genes, including IL-8, Lin28B, Let-7, IL-1α, IL-1β, IL-1, and vascular endothelial growth factor (VEGF), preventing cellular proliferation and transformation." (PMID 30765814, 2019).
cancer (continued). "Furthermore, we observed the enhanced secretory phenotype of cancer cells with massive production of pro-inflammatory cytokines, IL1β, IL6 and IL8, as well as death ligands, FAS-L and TRAIL, after combined treatment of GBM cells." (PMID 30783513, 2019). "Next, we inhibited IL1β by neutralising antibody in cancer cells, prior to treatment with CM." (PMID 31676788, 2019). "We then explored the mechanism by which cancer cell debris induces IL-1β production." (PMID 31588122, 2019). "Altogether, these studies raise the possibility that the IL-1β signaling could be therapeutically disrupted to improve chemotherapeutic efficacy in cancer patients." (PMID 31492049, 2019). "Collectively, these studies show how IL-1β regulates miRNA expression in cancer." (PMID 31557902, 2019). "Recent studies indicate that inflammation mediated by IL-1β may have a major role in cancer invasiveness, progression, and metastases." (PMID 31139332, 2019). "Interestingly, a subgroup analysis showed that the responsiveness of IL-1β was significantly correlated with the overall survival rate of cancer patients." (PMID 31041568, 2019). "The expression profile of IL-1β in the different tissues affected by cervical conditions was similar to that of IL-18, with a significant decrease in the mRNA expression levels between normal controls and cancer, as well as between LSIL and cancer." (PMID 31554368, 2019). "This suggests that IL-1β plays an important role in the treatment of cancer by S.t-ΔpGlux/pT-ClyA." (PMID 31754923, 2019). "As such, anti-IL-1β monoclonal antibodies (i.e., canakinumab) and IL-1β blockers (i.e., rilonacept) have been developed and show reduced cell proliferation, angiogenesis and metastasis of cancer cells in mice and in humans." (PMID 31374832, 2019). "Based on the results of our study, and in view of the ability of genistein to regulate the expression of miR-451, IL1β, and Cab39, we speculate that miR-451 and its target genes are also involved in the anti-cancer effects of genistein." (PMID 31816816, 2019). "Thus, in the present study, upregulation of IL-1β was observed, indicating that engineered S. typhimurium secreting lux/pT-ClyA enhances cancer immunotherapy by inducing IL-1β expression through two pathways." (PMID 31754923, 2019). "Multiple studies suggest that IL-1β may be valuable target for both the prevention and treatment of cancer and cancer therapy–related complications." (PMID 31139332, 2019). "Targeting the IL-1β/G-CSF axis might be relevant in certain cancer types that rely on NET-dependent prothrombotic states." (PMID 31552036, 2019). "Thus, IgG-induced activation of FcγRI/III-SYK signalling appeared to enhance NF-κB signalling and promote IL-1β production in the presence of cancer cell debris." (PMID 31588122, 2019). "IL-1β can adjust the malignant characteristics of cancer cells." (PMID 31492049, 2019). "Similarly, exposure of NT2 (NTera-2) “preneuronal” carcinoma cells to the inflammatory cytokine IL-1β elicited upregulation of ApoE and of p38/MAPK innate-immune signaling—responses that were fully blocked by PNR502." (PMID 31920540, 2019). "IL-1β could stimulate the accumulation of MDSCs in cancer and MDSCs is also argued to play a significant pro-inflammatory role by inducing Th17 development in an IL-1β-dependent manner." (PMID 29499727, 2018). "Furthermore, IL-1β promotes cancer cell adhesion and hepatic metastases by up-regulation of vascular cell adhesion molecule (VCAM-1) on hepatic sinusoidal endothelium." (PMID 30042333, 2018). "Cancer cells treated with recombinant IL1α or IL1β upregulate the expression of those same cytokines, suggesting that secretion of IL1α or IL1β in a few cancer cells could lead to the upregulation of both cytokines in neighboring cancer cells." (PMID 29777109, 2018).
cancer (continued). "Although there were major differences between cancer cell line exposed- and mf-exposed monocytes, mRNA expression of IL-1β, MMP9, and TGM2 was shown to be significantly upregulated in monocytes following exposure to either stimuli compared to unexposed monocytes." (PMID 29668679, 2018). "In the same study, the authors also showed that as a result of silencing IL-1A in pancreatic tumour cells (PaTu), CCL22 production was inhibited in PBMC, whereas inhibition of IL-1A or IL-1B in mammary 4T1 cancer cell line resulted in impaired CCL22 production in splenocytes." (PMID 29760166, 2018). "Several drugs used for cancer treatment were shown to induce IL-1β production, which may lead to unwanted side effects." (PMID 30042333, 2018). "Moreover, IL-1β stimulates the production of reactive oxidative species that induce DNA damage and cancer development." (PMID 30619282, 2018). "For instance, cachectic cytokines such as tumour necrosis factor-α (TNF-α), interferon-γ (IFN-γ), and different interleukins (ILs., e.g. IL-1β and IL-6) may be increased in the peripheral circulation of cancer patients and induce cancer cachexia." (PMID 29609556, 2018). "Moreover, we provide novel evidence that mutant KRAS is indirectly responsible for non-canonical NF-κB activation, which is IKKa and RelB based, via sensitization of cancer cells to host IL-1β." (PMID 29445180, 2018). "Notably, both IL-1α and IL-1β are crucial components of the pro-inflammatory secretory profile of senescent cancer cells as detailed below." (PMID 30154786, 2018). "The nasty outcomes of the cooperation between Notch and IL-1β in cancer may be potentiated by body metabolism, specifically by leptin, a hormone whose levels are significantly increased with obesity." (PMID 30154786, 2018). "In contrast, IL-1β has been shown to play a role in the development of the premetastatic niche and targeting the inflammasome-IL-1β pathway been proposed to provide a novel approach for the treatment of cancer." (PMID 30365491, 2018). "Additionally, the IL-1β gene is linked to the invasiveness of TNBC cells, and certainly, downregulation of this gene will reduce cancer cell proliferation, invasion, and metastasis." (PMID 30059519, 2018). "IL-1β is the most extensively investigated inflammasome-related cytokine in cancers." (PMID 28865486, 2017). "It is well established that, caspase-1 primarily activates IL-1β and IL-18 in cancer." (PMID 28974683, 2017). "The inflammatory cytokines released by immune cells in response to the presence of the cancer, such as interleukin-1β(IL-1β), interleukin-6 (IL-6) and tumor necrosis factor-α (TNF-α), have been shown to play a key role in the disturbances of appetite and body weight control." (PMID 29207625, 2017). "IL-1R1 antagonist (IL-1Ra) completely abolish IL-1β-induced enhancement of nociceptive neuron responses and produce anti-allodynic effects in rat model of neuropathic, inflammatory, and cancer pain." (PMID 28645297, 2017). "However, recent studies are inclined to interpret IL-1β as a pro-cancer factor due to its immunosuppressive and chemoresistant properties." (PMID 28360909, 2017). "Consistent with this, short-term exposure of cancer-associated fibroblasts, mesenchymal stem cells, and osteoblasts to pH 6.8 promotes the expression of inflammatory and nociceptive mediators (NGF, BDNF, IL6, IL8, IL1b and CCL5)." (PMID 28903357, 2017). "Considering the pathogenic roles of IL-1β, NF-kB, ERK1/2, and NALP3 inflammasome inappropriate activation in a large number of major human disorders and in cancer, a large interest is focused on the identification of molecules able to target them, in order to develop new therapeutic agents." (PMID 28331244, 2017). "The capacity of NAI and NAI-imine to enhance P2X7-induced IL-1β release from macrophages may have implications in cancer therapy." (PMID 27524862, 2016). "At present, the role of NLRP3 inflammasome and IL-1β in cancer is highly controversial." (PMID 27672241, 2016).